IL6 (interleukin 6)
Diseases named in the same sentence as IL6 in open-access papers (continued):
Sharing a sentence is not in itself a finding about the gene and the disease.
autoimmune disease (continued). "Elevations in CRP, fibrinogen, and ferritin, key acute-phase reactants are characteristic of autoimmune diseases such as RA, reflecting systemic inflammation and complementing the inflammatory cascade driven by pro-inflammatory cytokines, particularly interleukin-6 (IL-6)." (PMID 40757204, 2025). "Clinically, JAK inhibitors (e.g., tofacitinib) already approved for autoimmune diseases show promise in preclinical models by reducing IL-6/STAT3-driven EMT, while TLR4 or NLRP3 inhibitors could blunt the initial DAMP-induced inflammatory cascade that seeds EMT." (PMID 41019090, 2025). "B cells exhibit dual immunomodulatory functions in T-cell-mediated autoimmune diseases, demonstrating both protective effects through regulatory cytokine secretion (e.g., IL-10) and pathogenic contributions via proinflammatory mediators (including TNF-α, IL-6, and GM-CSF)." (PMID 40691766, 2025). "Furthermore, the interplay between IFNβ and IL-6 is likely to be affected in the context of the use of jakinibs, small-molecule therapeutics for autoimmune disease that inhibit the activity of one or more of the Janus kinase (JAK) enzymes to shape the STAT signaling in immune cells." (PMID 40519931, 2025). "It promotes the production of IL-6 and IL-23 through CD11c* lamina propria DCs and can induce the proliferation and differentiation of Th-17 in the small intestine to play an anti-infective role, which may be related to the occurrence of autoimmune diseases." (PMID 38475833, 2024). "Additionally, an anti-IL-6 CAR Treg could be an effective way of treating RA or other IL-6 mediated autoimmune diseases." (PMID 39445021, 2024). "It was shown that rCpstefin had a potential modulatory effect on macrophage inflammation, which suggested that rCpstefin could be further applied to the study of autoimmune diseases characterized by a significant increase in IL-1β, IL-6, and TNF-α, such as inflammatory bowel inflammation." (PMID 38792680, 2024). "Although further investigation is needed, the examination of the frequencies of the −174G>C IL-6 promoter polymorphism and HFE mutations may add some valuable information on the interplay linking iron metabolism, inflammation and immunity in autoimmune diseases such as SLE and RA." (PMID 38003490, 2023). "Thus, our findings highlight the possible biological relevant ligand for IL-6R, which is of great importance for filling out the current knowledge of the IL-6/IL-6R/gp130 buffer system, and provide a potential inhibitor for clinical application in autoimmune diseases." (PMID 38015631, 2023). "IL-6 is a mediator engaged in the regulation of the acute phase response to damages and infections, whereas its dysregulation may result in the development of autoimmune diseases (RHs, MS)." (PMID 38202792, 2023). "However, many studies related IL-6 overexpression to autoimmune diseases and cancer." (PMID 37658354, 2023). "Systemic lupus erythematosus is an autoimmune disease, during the course of which the occurrence of hematological and other organ manifestations is a significant clinical problem, and a variety of cytokines, such as IL-4, IL-6, and interleukin 10 (IL-10), can have a significant impact on this." (PMID 38139169, 2023). "Therefore, TNF-α and IL-6 are well known to be related to autoimmune diseases such as rheumatism." (PMID 36039384, 2022). "Therefore, TNF-α and IL-6 are related to a wide range of inflammatory or autoimmune diseases." (PMID 34888304, 2021). "It is necessary to determine the relationships between sleep and IL-6, because this is a critical signaling molecule in the immune response to pathogens, and chronically elevated levels are related to the onset of cardiovascular, metabolic and autoimmune diseases." (PMID 33579032, 2021).
autoimmune disease (continued). "IL-6 can be produced by macrophages and has pleiotropic functions in immune system, which activates immune cells to remove pathogens, to repair damaged tissues, to regulate acute immune response and is also involved in autoimmune diseases and chronic inflammation." (PMID 33968087, 2021). "In addition, pIL6RmAb may also help to address the high-cost issues of therapeutics for treating RA and other autoimmune diseases as it retains the IL-6 blocker activity of sarilumab." (PMID 34835296, 2021). "IL-6 may promote autoimmune disease by promoting the production of T-helper 17 (Th17) cells." (PMID 34696354, 2021). "Increased expression of the proinflammatory cytokine Interleukin-6 (IL-6) in DCs of Prdm1 CKO mice, following Toll-like receptor (TLR) 4 stimulation, leads to an enhanced differentiation of follicular helper T cells (TFH), revealing a potential pathogenic mechanism for PRDM1 in autoimmune diseases." (PMID 32765503, 2020). "Additionally, IL-6 trans-signaling can increase IL-6 activity under inflammatory environment and to further prevent the apoptosis of T cells, which probably play a crucial role in the exacerbation and the prolongation of autoimmune disease processes." (PMID 32117217, 2020). "Moreover, IL-6 is a major cytokine involved in different autoimmune diseases." (PMID 32806551, 2020). "Considering that the level of IL6 can raise many thousand-fold in the course of inflammation and autoimmune diseases, we believe that MSCs preconditioning with Vadadustat may appear to be a very promising approach for the use in therapy of autoimmune diseases." (PMID 33139632, 2020). "Since numerous chronic inflammatory and autoimmune diseases are mediated by interleukin (IL)-6-induced T helper (TH) 17 cells, a TH17-directed anti-inflammatory therapy may be preferable to an IL-12-dependent TH1 inhibition in order to avoid reactivation of latent infections." (PMID 33375150, 2020). "In addition, SARS-CoV-2 infection can activate NF-κB, leading to multiple inflammatory and autoimmune diseases, which induces pro-inflammatory cytokines and chemokines, including IL-6, and recruits lymphoid cells and myeloid cells, such as activated T cells and macrophages." (PMID 33132913, 2020). "However, IL-6 has also been shown to stimulate inflammatory processes as a pro-inflammatory cytokine in a wide range of diseases including cancers and metabolic, cardiovascular, neurologic, and autoimmune diseases." (PMID 32093397, 2020). "LPS stimulates the secretion of proinflammatory cytokines by macrophages such as TNF-á and IL-6 which are critical to the initiation of the inflammatory response; however, hypersecretion of proinflammatory cytokines ultimately result in inflammatory-related diseases or autoimmune diseases." (PMID 30909606, 2019). "Recently, it was found that TGFß, together with IL-6, drives the initial differentiation from naïve T-cells to pathogenic IL-17-producing T-cells (TH17 cells), which are key factors for induction of tissue damage in a variety of chronic inflammatory and autoimmune diseases." (PMID 31694340, 2019). "Therefore, we speculate that in the process of the development of autoimmune diseases, IL-6 likely has a direct or indirect effect on TFR cells and thereby promotes the occurrence of disease." (PMID 29312316, 2017). "Since our data demonstrated that BVDU could inhibit IL-6, IL-12, IL-23 and IL-1β production in DCs, and these pro-inflammation cytokines played a critical role in initiating the autoimmune disease, we hypothesized that this drug might have promising potential in treating autoimmune disease." (PMID 28272439, 2017). "Also type II IFN/IFNγ was found to remarkably enhance the production of IL-6 by neutrophils treated with R848, further highlighting the capacity of these cells to fully respond to the interferon-induced signals during viral and autoimmune diseases." (PMID 26790609, 2016).
autoimmune disease (continued). "Therefore, blocking agents directed towards IL-6 or the IL-6 receptor might be a possible strategy to treat autoimmune diseases." (PMID 26193267, 2015). "Furthermore, IL6 plays a major role in B cell differentiation and T cell proliferation, and the deregulated production of IL6 and its receptor was related with the pathogenesis of autoimmune diseases by inhibition of autoreactive T cell apoptosis." (PMID 25127106, 2014). "Tocilizumab (Actemra, Chugai Pharmaceutical Co., Ltd., Tokyo, Japan), a humanized anti-human IL-6 receptor (IL-6R) monoclonal antibody that inhibits IL-6 binding to IL-6R might inhibit the biologic function of IL-6, which plays a pivotal role in the pathogenesis of autoimmune diseases." (PMID 23424706, 2012). "Thus, the IL-6 amplifier, which is chronically activated by these four events, is a critical regulator of chronic inflammations in tissue-specific MHC class II-associated autoimmune diseases." (PMID 23162547, 2012). "IL-6 in the presence of TGF-β promotes naïve T-cell differentiation into Th17 cells, while IL-6 inhibits TGF-β-induced regulatory T-cell (Treg) differentiation, causing imbalance between Th17 and Treg, which is a primary pathogenic factor in several autoimmune diseases." (PMID 22315615, 2012). "Hence, the IL6 cytokine pathway is a nodal point in the shaping of an adaptive immune response and we believe that sexual dimorphism in autoimmune diseases is a result of differing cytokine pathways being involved in the regulation of Th cell network homeostasis." (PMID 23148845, 2012). "In autoimmune disease, where Th1/Th17-macrophage circuits dominate, steroid-sparing treatment targets TNF and IL-6 pathways." (PMID 41877771, 2026). "IL-6 and TNF-α are well known to be involved in pathogenesis of chronic inflammation, autoimmune diseases, and cancer." (PMID 40496000, 2025). "Several disease markers are often seen in autoimmune diseases, such as IL-6, IL-1β, and tumor necrosis factor-α (TNF-α), with IL-6 being one of the key markers." (PMID 39968418, 2025). "These single-cytokine secretion profiles, involving the production principally of IL6, IL12 or IL17, are nonetheless of interest for the control of other diseases, such as inflammatory diseases, autoimmune diseases and cancers." (PMID 40181981, 2025). "In another study, multivalent aptamers that target IL-6 and TNF-α were intended to control inflammatory responses in autoimmune disorders." (PMID 40870970, 2025). "Autoimmune diseases are characterized by Th1/Th17-polarized environment and elevated cytokines of pro-inflammatory types (e.g., TNF-alpha, IL-6, IL-17A, IFN-gamma) advancing immune-mediated inflammation and immune-cell-mediated destruction." (PMID 41465368, 2025). "Elevated serum interleukin-6 (IL-6) levels have been shown to correlate with disease activity in patients with thyroid eye disease (TED), a complex, heterogeneous, autoimmune disease affecting thousands of people worldwide." (PMID 40297767, 2025). "Pro-inflammatory cytokines such as IL-6, TNF-α, and BAFF are upregulated in multiple autoimmune diseases, making them valuable for monitoring disease activity but less reliable for differentiating between conditions." (PMID 40095875, 2025). "The results indicate that the compounds MJ19 and MJ20 have the greatest effect on the induction of pro-inflammatory (IL6, IL8) and antiapoptotic (BCL2, MDM2) genes, suggesting their potential use in therapies for inflammatory and autoimmune diseases." (PMID 40725171, 2025). "Consistent with other autoimmune disorders, PBC pathogenesis involves elevated inflammatory factors (IL-6, IL-8, IL-10, TGF-β) and immune cell infiltration, particularly CD4 + and CD8 + T lymphocytes." (PMID 41144108, 2025). "Under the combined induction of TGF-β and IL-6, naive CD4+ T cells differentiate into Th17 cells secreting IL-6 and IL-17, participating in inflammatory responses and autoimmune diseases." (PMID 40557038, 2025).
autoimmune disease (continued). "In another separate research, multivalent aptamers that target IL-6 and TNF-α were designed to control inflammatory reactions in autoimmune disorders." (PMID 40870970, 2025). "The IL-6/JAK/STAT signaling pathway is involved in the pathogenesis of various inflammatory and autoimmune diseases, and JAK inhibitors are emerging as promising new therapeutics for the treatment of autoimmune diseases." (PMID 39643607, 2024). "Dysregulation of TIM-3 expression has been associated with excessive or inhibited inflammatory responses, leading to autoimmune disease and pregnancy complications, while TNF-α and IL-6 have a well-documented role in TAI pathogenesis." (PMID 39595192, 2024). "M1 macrophages are prevalent in the pro-inflammatory environment of autoimmune diseases such as Systemic Lupus Erythematosus (SLE), and thus produce cytokines such as IL-1β, interferon (IFN-γ), and IL-6." (PMID 39329752, 2024). "IL-6, along with C-reactive protein (CRP), is commonly used as a serum biomarker to monitor inflammation in patients with cancer, infection, or autoimmune diseases due to its crucial role in activating and sustaining the inflammatory response." (PMID 37760027, 2023). "Specifically, in autoimmune diseases like systemic lupus erythematosus (SLE), estrogen stimulates the expression of IL-6, which drives naive CD4 cells to differentiate into Th17 cells and inhibits TGF β of IL-6, which drives naive." (PMID 37215125, 2023). "Dysregulated production of IL6 and IL6R has been suggested to contribute to the pathogenesis of many diseases, such as prostate cancer, multiple myeloma, and autoimmune diseases." (PMID 38140161, 2023). "The action of IL-6 can be blocked by anti-IL-6R antibody, e.g., tocilizumab or ALX-0061, which effectiveness was proven for autoimmune disease treatment." (PMID 40589521, 2023). "IL6 is related to the pathogenesis of autoimmune diseases and the AKT/NF-κB signaling pathway has been reported to contribute to IL6 production in the retrobulbar space during GO activity." (PMID 35462920, 2022). "The IL-6 also interacts with TGF-β and promotes T-helper 17 (Th17) cell differentiation, which drives further inflammation and exacerbates autoimmune disease." (PMID 36397759, 2022). "As a result, using PSL in combination with 114 increased the concentration of Th2 cytokines, such as IL-6, suggesting that this combination could potentially restructure Th1 and Th2 composition (toward Th2 dominant) and improve the clinical state of Th1-mediated autoimmune diseases." (PMID 35265152, 2022). "Previous study also reported a distinct low-density granulocyte (LDG) as an immature neutrophil subtype with a stronger capacity to produce NETs and proinflammatory cytokines (IL-6, type I IFN, etc.)in some autoimmune diseases." (PMID 35854322, 2022). "In fact, it was previously revealed in mice encoding a genetic deletion of this gene shall exacerbate the autoimmune disease EAE by increased production of proinflammatory cytokines such as TNF-α, IL-6, and IL-17 in the CNS and lymph nodes." (PMID 34980262, 2022). "For example, IL-6 and IL1B were confirmed to be involved in the regulation of the inflammatory response and the development of various autoimmune diseases, including RA, and were effective targets for treatment." (PMID 36439145, 2022). "Vitiligo is considered to be an autoimmune disease because cytokines such as (IFN)-γ, IL-1, IL-6, IL-8, and IL-10 are overexpressed in lesions, and activated CD8 + T lymphocytes, TH17, and other immune cells are significantly aggregated in the lesion area." (PMID 33790887, 2021). "Moreover, they found that lncRNAs may be involved in the upregulation of genes belonging to the type α- and β-interferon signaling pathways, as well as the increased regulation of interleukin-6 (IL-6), a cytokine playing a major role in inflammatory and autoimmune diseases." (PMID 34573278, 2021).
autoimmune disease (continued). "Proinflammatory cytokines such as IL-1β, IL-6, and TNF-α, which play crucial roles in the development of inflammatory diseases, are also involved in the innate immunity and autoimmune diseases." (PMID 34824594, 2021). "IL-6 production is stimulated by systemic viral infection (e.g., HHV-8, HIV), autoimmune diseases, hematologic disorders of lymphocytes, KS, and even by itself through a paracrine process." (PMID 34930492, 2021). "It should be remembered that IL-1, IL-6, transforming growth factor (TGF)-β, and IL-23 favor the differentiation of Th17 cells, which have a widely demonstrated role in the etiology of autoimmune diseases and allergic diseases." (PMID 34445745, 2021). "Th17 cells are a subset of CD4+ helper T cells, which are widely believed to induce inflammation in the pathogenesis of autoimmune diseases by producing cytokines such as IL‐17, TNF‐α, and IL‐6." (PMID 33728820, 2021). "SARS-CoV-2 activated NF-κB and STAT3 through the AngI–AT1R pathway after SARS-CoV-2 infection, and then activated IL-6 amplifier (IL-6 Amp), which was a mechanism for STAT3 to overactivate NF-κB and led to various inflammations and autoimmune diseases." (PMID 34858386, 2021). "In the present study, through the analysis of the PPI network of DE mRNAs, we identified several hub genes, including IL6, IL10, and CXCL8, which are important genes in autoimmune diseases and inflammatory pathways." (PMID 34284720, 2021). "IL6 promotes the differentiation of CD4+ T-helper (Th) cells into Th17 cells, thereby contributing to the pathogenesis of autoimmune diseases." (PMID 32458144, 2020). "In contrast, autoimmune disorders (e.g., SLE) have a strong contribution of IL-6 highlighted by successful anti-IL-6 treatment." (PMID 29515565, 2018). "B cells, identified by releasing IL-10, IL-35, and TGF-β, had been shown to limit inflammation, autoimmune disease, and tumor, while B cells, identified by secreting TNF-α, IL-6, and GM-CSF, had been shown to promote disease." (PMID 28831210, 2017). "Th17 cells, a key player in autoimmune diseases and antibiosis, are differentiated from naïve T cells (CD4+) stimulated by IL-6, TGF-β, IL-1β, IL-21 and IL-23 and release IL-17A, IL-17F, IL-21 and IL-22." (PMID 28899359, 2017). "Thus, the current view is that IL-6, especially in combination with TNFα, is capable of inducing Tcon cells to resist Treg suppression, providing an attractive therapeutic target for reducing inflammation and restoring suppressive balance in autoimmune disease." (PMID 27242798, 2016). "Furthermore, it would be of particular interest to determine whether the increase in serum VIP levels reported with TNF blockers is class-specific or is also observed in autoimmune disorders treated with other biological therapies, such as blockade of interleukin (IL)-6 or IL-12 signaling." (PMID 25711477, 2015). "Th17 cells are characterized by the production of various proinflammatory cytokines including IL-6, IL-17, IL-21, and TNF-α, and play crucial roles in the pathogenesis of various autoimmune diseases, including RA." (PMID 26544846, 2015). "IL-17, which can be secreted by Th17 cells, was treated as a therapeutic target in some autoimmune disease, which promote secretion of multiple inflammation factors like TNF-α, IL-1, IL-6 and IL-8." (PMID 26677348, 2015). "Restricted cubic spline analysis and subgroup analysis showed that the lowering effect of marine-derived n-3 PUFAs on CRP, IL-6 and TNF-α in subjects with chronic non-autoimmune disease became weakened when body mass index was greater than 30 kg/m2." (PMID 24505395, 2014). "The present meta-analysis provided consistent evidence that marine-derived n-3 PUFAs supplementation had a significant lowering effect on fasting blood levels of CRP, IL-6 and TNF-α in subjects with chronic non-autoimmune disease and healthy subjects." (PMID 24505395, 2014).